KANK3 (KN motif and ankyrin repeat domains 3)
Description:
May be involved in the control of cytoskeleton formation by regulating actin polymerization.
Synonyms: ANKRD47; FLJ46061
Tractability: Antibody: the Human Protein Atlas places it where antibodies can reach.
Gene: Protein-coding gene on chromosome 19 (8,322,582 to 8,343,268, reverse strand). Ensembl gene ENSG00000186994.
Subcellular location (Human Protein Atlas): Plasma membrane
Gene Ontology:
Biological process: negative regulation of actin filament polymerization
Cellular component: cytoplasm; cytoskeleton
Genetic constraint (gnomAD): Loss-of-function variants: 59 observed, 43.78 expected, observed/expected ratio (o/e) 1.35, 90% interval 1.09 to 1.67. The synonymous counts are far from expectation, so gnomAD's model fits this gene poorly and the ratio says little. Missense variants: 1,168 observed, 881.28 expected, observed/expected ratio (o/e) 1.33, 90% interval 1.26 to 1.39. Synonymous variants: 576 observed, 399.16 expected, observed/expected ratio (o/e) 1.44, 90% interval 1.35 to 1.55.
Homologues: Orthologues: chimpanzee KANK3 (96% identical), macaque KANK3 (92% identical), rabbit KANK3 (84% identical), dog KANK3 (81% identical), pig KANK3 (79% identical), rat Kank3 (76% identical), mouse Kank3 (75% identical), Drosophila melanogaster Kank (25% identical), Caenorhabditis elegans vab-19 (23% identical). Paralogues in human: KANK1 (35% identical), KANK2 (29% identical), KANK4 (27% identical).
Diseases named in the same sentence as KANK3 in open-access papers:
KANK3 is named in the same sentence as 9 diseases in open-access papers, as found by Europe PMC text mining. Sharing a sentence is not in itself a finding about the gene and the disease. The quoted sentences say what the papers report.
Hernia (1 paper, 2020). "This indicates a possible pleiotropic effect of KANK3 in the manifestation of various types of hernias in pigs." (PMID 32379844, 2020).
Inguinal hernia (1 paper, 2020). Protrusion of the contents of the abdominal cavity through the inguinal canal. "The KANK3 gene was downregulated in the affected animals and has been mapped to a QTL region for umbilical hernia and for scrotal/inguinal hernia." (PMID 32379844, 2020). "Moreover, three other DE genes found in our study were located in QTL regions for scrotal/inguinal hernias: ACAN mapped in SSC7, Butyrylcholinesterase (BCHE) in SSC13 and KANK3 in SSC2." (PMID 32379844, 2020).
prostate carcinoma (1 paper, 2025). A carcinoma that arises from epithelial cells of the prostate gland. "Functional mechanism studies confirmed that KANK3 acts as a key tumor suppressor gene in prostate cancer, and its expression silencing is closely associated with tumor aggressive phenotypes and PARP inhibitor resistance." (PMID 41049009, 2025). "Among these, only KANK3 exhibited a statistically significant differential expression between prostate cancer and normal prostate tissues." (PMID 41049009, 2025). "Experiments verified that KANK3, a key hub gene in the model, had low expression in prostate cancer but was up - regulated post - treatment." (PMID 41049009, 2025). "Furthermore, immunohistochemical analysis was employed to validate the expression of KANK3 in normal prostate tissues and prostate cancer lesions." (PMID 41049009, 2025).
Umbilical hernia (1 paper, 2020). Protrusion of abdominal contents through a defect in the abdominal wall musculature around the umbilicus. "Therefore, KANK3 become a strong functional candidate to the development of umbilical hernia in pigs." (PMID 32379844, 2020).
tumor (4 papers, 2021 to 2025). "Prior investigations have suggested that KANK3 functions as a tumor - suppressor gene; however, its implications in the context of PCa have yet to be documented in the scientific literature." (PMID 41049009, 2025). "In some tumor types, KANK3 also exhibits unique expression patterns and functions." (PMID 41049009, 2025). "The KANK family plays roles in actin cytoskeleton organization and cell motility; however, KANK3 functions are not well understood, and KANK3 might act as a tumor suppressor." (PMID 36139015, 2022). "Mechanistically, we experimentally validate KANK3, a key PIRG identified by the model, as a functional tumor suppressor that inhibits cell proliferation by negatively regulating Ki67 expression." (PMID 41049009, 2025).
cancer (3 papers, 2021 to 2025). A tumor composed of atypical neoplastic, often pleomorphic cells that invade other tissues. "KANK3 has the potential to interact with other proteins or signaling pathways within cancer cells, and understanding these interactions will provide a more comprehensive view of its function." (PMID 41049009, 2025). "Therefore, the KANK3 protein might be a candidate for improving cancer therapy." (PMID 35559038, 2022).
KANK3 also shares sentences with these, for which no sentence is quoted: hepatocellular carcinoma (2 papers); leukemia (1); liver cancer (1).